CD33 (CD33 molecule)
Diseases named in the same sentence as CD33 in open-access papers (continued):
Sharing a sentence is not in itself a finding about the gene and the disease.
acute myeloid leukemia (continued). "Gemtuzumab ozogamicin, a humanized murine IgG4 anti-CD33 antibody, is the first antibody–drug conjugate approved for acute myeloid leukemia (AML)." (PMID 35327591, 2022). "Gemtuzumab ozagamicin and lintuzumab are two CD33 antibodies that have been extensively tested in patients suffering from acute myeloid leukemia (AML)." (PMID 33867926, 2021). "The CD13 and CD33 antigens and myeloperoxidase that characterize normal myeloid progenitors are abundantly expressed on almost all acute myeloid leukemia (AML) cells." (PMID 34203180, 2021). "Later, development of antibody humanization techniques and conjugation to more potent drugs contributed to the approval in 2000 by the FDA of the first ADC (Gemtuzumab ozogamicin), raised against the CD33 molecule for acute myeloid leukemia (AML) treatment." (PMID 33081391, 2020). "The same strategy was adapted for an anti-CD33 CAR for treatment of acute myeloid leukemia (AML) cells, which express high levels of the CD33 antigen." (PMID 32679920, 2020). "For instance, both healthy and cancerous myeloid cells express CD33 and therefore traditional CD33 CAR T-cell therapy of acute myeloid leukemia (AML), which is in phase I and I/II clinical trials, would disrupt non-cancerous normal cells too." (PMID 32973401, 2020). "The safety of CAR NK-92 cells was tested in acute myeloid leukemia (AML) patients in a recent “first-in-man” clinical trial targeting CD33." (PMID 33287875, 2020). "One example is an early clinical trial with AML (acute myeloid leukemia) patients treated with an anti-CD33 calicheamicin (gentuzumab ozogamicin, aka Mylotarg)." (PMID 31891584, 2019). "As a result, GO was reapproved by the FDA for the treatment of newly-diagnosed CD33-positive acute myeloid leukemia (AML) in adults and for treatment of relapsed or refractory CD33-positive AML in adults and in pediatric patients 2 years and older." (PMID 31434267, 2019). "A first generation ADC, gemtuzumab ozogamycin (GO/Mylotarg) targeting CD33 was approved by the FDA in 2000 to treat acute myeloid leukemia (AML)." (PMID 29409507, 2018). "With the demonstration of improved survival of some acute myeloid leukemia (AML) patients with the CD33 antibody-drug conjugate, gemtuzumab ozogamicin (GO), CD33 has been validated as a target for antigen-specific immunotherapy." (PMID 27248327, 2016). "In a separate study, heteroclitic-variants of CD33, a cell surface glycoprotein restricted to myeloid lineage cells, effectively generated acute myeloid leukemia (AML)-specific CTL, that did not lyse or inhibit the proliferation of normal CD34+ progenitor cells." (PMID 26257743, 2015). "Previously, we showed that discoidin domain receptor 1 (DDR1), a class of collagen-activated receptor tyrosine kinase (RTK) was highly upregulated on bone marrow (BM)-derived CD33+ leukemic blasts of acute myeloid leukemia (AML) patients." (PMID 24519883, 2014). "Previously, we showed for the first time that discoidin domain receptor 1 (DDR1), a class of collagen-activated receptor tyrosine kinase (RTK), was highly upregulated on BM-derived CD33+ leukemic blasts of acute myeloid leukemia (AML) patients." (PMID 24519883, 2014). "CD33 is a myeloid-specific sialic acid-binding receptor overexpressed on the cell surface of 90% of acute myeloid leukemia (AML) blasts." (PMID 22272203, 2012). "Aliperta and colleagues described a novel approach to immunotherapy for acute myeloid leukemia (AML) in which genetically modified human MSCs were utilized as autonomous factories for the production of anti-CD33-anti-CD3 bi-specific antibodies (MSCsanti-CD33-anti-CD3)." (PMID 40643499, 2025). "A variety of anti-CD33 CAR-T cell constructs have shown significant preclinical therapeutic effects on primary acute myeloid leukemia (AML) cells in vitro and in humanized animal models, and their toxic effects on leukemia cells and non-leukemia myeloid cells have also been observed." (PMID 40129984, 2025).
acute myeloid leukemia (continued). "Similarly, CAR-NK cells designed to target specific leukemia antigens, such as CD19 and CD33, have demonstrated greater cytotoxicity and specificity against acute myeloid leukemia (AML) cells." (PMID 39911388, 2025). "Research is ongoing on CD33-deleted hematopoietic stem and progenitor cell (HSPC) therapies for acute myeloid leukemia (AML) (NCT05662904)." (PMID 40801569, 2025). "At present, in a clinical trial report of anti-CD33 CAR-T cell therapy, the treatment of a patient with refractory acute myeloid leukemia (AML) was recorded in detail." (PMID 40129984, 2025). "For example, both CD33 and CD123 are highly expressed in acute myeloid leukemia (AML) cells, providing significant clinical therapeutic effects but also significant toxic side effects." (PMID 38919533, 2024). "The presence of myelomonocytic specific markers, such as CD13, CD15, CD33, myeloperoxidase (MPO), CD14, and CD64 is useful for establishing the diagnosis of CD56‐positive acute myeloid leukemia, first presenting in the skin." (PMID 39210931, 2024). "We report preclinical studies on a CD33 x CD3 bivalent bispecific diabody, AMV564, that not only suppresses tumor growth, but also facilitates memory responses in a mouse model of acute myelogenous leukemia (AML)." (PMID 38696390, 2024). "The construction of another BiKE construct, which acts through CD16 while also targeting the myeloid differentiation antigen CD33, could induce the degranulation and lytic ability of NK cells towards acute myeloid leukemia (AML) cells in vitro." (PMID 39339180, 2024). "Various antigens, including CD33 and CD123, which are overexpressed on acute myeloid leukemia (AML) leukemic stem cells, have been extensively studied in preclinical models." (PMID 38259840, 2023). "Since the first ADC, Mylotarg® (gemtuzumab ozogamicin), was approved in 2000 by the US Food and Drug Administration (FDA) against CD33-positive acute myeloid leukemia (AML), there have been 14 ADCs received market approval, and over 100 ADCs are currently under clinical development." (PMID 36776873, 2023). "Similarly, on acute myeloid leukemia (AML) cell lines, decitabine was found to improve the effectiveness of CD33-CAR-T cells by enhancing the expression of CD33." (PMID 38201467, 2023). "In May 2000, FDA approved the first ADC, gemtuzumab ozogamicin (Mylotarg), a humanized monoclonal antibody (gemtuzumab) conjugated with drug (ozogamicin) targeting CD33 protein, made by Wyeth for the treatment of patients with acute myeloid leukemia (AML)." (PMID 37671162, 2023). "Lintuzumab-CD28/CD3ζ CD33 CAR-T immunotherapy is now under evaluation in a preclinical trial involving children and adolescents/young adults with relapsed/refractory acute myeloid leukemia (AML)." (PMID 38136311, 2023). "A novel second-generation anti-CD33 CAR that incorporated a 4-1BB-CD3ζ signaling tail has previously proven effective in clinical trials of both chronic and acute myeloid leukemia." (PMID 35267549, 2022). "CD33 is a favorable target for leukemia, especially acute myeloid leukemia (AML)." (PMID 36209106, 2022). "Vadastuximab talirine, an anti-CD33 antibody coupled to PBD, showed robust activity in acute myelocytic leukemia (AML) animal models." (PMID 36348391, 2022). "AMG 330, the first CD33 × CD3 BiTE applied for acute myeloid leukemia (AML) patients, has shown promising cytolytic activity against AML cells in preclinical studies even at low CD33 antigen densities on target cells, making it a candidate for targeting a broad range of CD33+ leukemias." (PMID 36389699, 2022). "The antibody conjugate gemtuzumab ozogamicin (GO; Mylotarg®) provides targeted therapy of acute myeloid leukemia (AML), with recent approvals for patients with CD33-positive disease at diagnosis or relapse, as monotherapy or combined with chemotherapeutics." (PMID 35690610, 2022).
acute myeloid leukemia (continued). "BiTE for acute myeloid leukemia (AML) targets proteins expressed on most AML blasts, such as CD33 and CD123, and cell surface proteins that are often overexpressed or mutated on AML blasts, such as FLT3." (PMID 36232824, 2022). "Furthermore, traditional CAR T-cell therapy of acute myeloid leukemia (AML) can target CD33 or CD7, which are expressed on normal hematopoietic stem cells (HSCs) and tumor cells." (PMID 34446084, 2021). "Although the applicability of CD19-directed CAR-T therapy in acute myeloid leukemia (AML) is limited, alternative leukemic cell-specific antigens such as CD33, CD38, CD56, CD117, CD123, Lewis-Y, and Muc-1 are currently being explored." (PMID 34203935, 2021). "It is also highly expressed in acute myeloid leukemia (AML), leading to the use of anti-CD33 antibody carrying a cytotoxic drug for cancer treatment." (PMID 34065256, 2021). "CD33 is a differentiation marker found on myeloid blast cells in acute myeloid leukemia (AML)." (PMID 33936029, 2021). "Another bsADC model was recently developed for CD7+/CD33+ acute myeloid leukemia (AML)." (PMID 34696218, 2021). "In acute myeloid leukemia, researchers applied cryogel-housed MSCs modulated to secrete a bispecific (anti-CD3 and anti-CD33) antibody for maximizing cancer immunotherapy." (PMID 33685452, 2021). "Herein, we identified Nbs against CD33, a marker for acute myeloid leukemia (AML)." (PMID 31906437, 2020). "For example, whilst CD33‐positive acute myelogenous leukaemia tumors express relatively low levels of target antigen (5000–10 000 receptors per cell), an ADC that targets the CD33 antigen still shows meaningful clinical response rates." (PMID 32685149, 2020). "CD33 is expressed at the level of hematopoietic cells, principally in circulating monocytes and dendritic cells, and is being actively targeted in acute myeloid leukemia (AML) cells." (PMID 33333862, 2020). "A second-generation CD33-specific CAR was generated and was proved to be effective for acute myeloid leukaemia." (PMID 28053197, 2017). "Hence, it might be worthwhile to explore if the repurposing of anti-CD33 antibodies/inhibitors developed for treating acute myelogenous leukemia (Gemtuzumab ozogamicin, Vadastuximab talirine, Lintuzumab, BI-836858, HuM195/rGel and HuM-195-Ac-225) are also effective for AD." (PMID 28005991, 2016). "Here we provide ‘proof of concept' for retargeting of UniCAR T cells to CD33- and/or CD123-positive acute myeloid leukemia blasts in vitro and in vivo." (PMID 27518241, 2016). "Antibodies/inhibitors targeting CD33 and MIF were originally tested in clinical trials for the treatment of acute myelogenous leukemia (AML) or solid tumors." (PMID 28005991, 2016). "Moreover, such curcumin immunoconjugates were shown to kill specifically tumor cells bearing the CD33 marker expressed by acute myeloid leukemia (AML) cells in patients synthetizing and expressing hCGβ on the cellular membrane." (PMID 25514225, 2014). "Additionally, immunoconjugates targeting CD33 are currently a valuable option to treat patients with acute myeloid leukemia (AML)." (PMID 21359217, 2011). "In acute myeloid leukemia (AML), the target CD33 has garnered widespread attention." (PMID 40843358, 2025). "Recent preclinical studies on dual targeting of acute myeloid leukemia with a transgenic NPM1-antigen-specific TCR and a CD33 CAR revealed that double transgenic receptor expression led to better cytotoxicity and tumor control relative to single receptor-expressing T cells." (PMID 41181132, 2025). "Gemtuzumab ozogamicin for acute myeloid leukemia initially received US accelerated approval for treatment of 60 years or older patients with relapsed CD33‐positive and not candidates for cytotoxic chemotherapy." (PMID 40178688, 2025). "A similar phenomenon has been observed with AMG 330 (CD33×CD3) in acute myeloid leukemia, where CD33-low/negative clones were detected in ~60% of patients who initially responded but later relapsed." (PMID 41262250, 2025).
acute myeloid leukemia (continued). "The coupling of the humanized monoclonal antibody (mAb) Gemtuzumab ozogamicin, which targets the CD33 antigen expressed in the hematopoietic system, to CAL enables precise targeting of transformed cells with minimal general cytotoxicity in acute myeloid leukemia (AML)." (PMID 40272602, 2025). "The acute myeloblastic leukemia with maturation (former AML-M2 FAB) is often positive for CD13, CD15, CD33, CD34, CD117, HLA-DR and comprises approximately 25-30% of all cases with ≥ 20% blasts in the bone marrow or peripheral blood with ≥ 10% granulocyte differentiation." (PMID 40313947, 2025). "Similarly, gemtuzumab ozogamicin, an antibody–drug conjugate targeting CD33, has been approved for the treatment of acute myeloid leukemia (AML) in CD33-positive patients, demonstrating significant improvements in response rates and overall survival, particularly among elderly individuals." (PMID 40723215, 2025). "Of note, CD33 and BCMA are specifically present in acute myeloid leukemia and in plasma cells and some B cells, respectively, so the payload mechanism of action could produce an ALT/AST increase or corneal toxicity." (PMID 40006625, 2025). "A second report describes a 68-year-old woman with acute myeloid leukemia and no detectable levels of surface CD33 protein." (PMID 40043053, 2025). "Therefore, despite CD33 being recognized as a promising molecular target in AML therapy, scientific knowledge about its functions in acute myeloid leukemia remains incomplete." (PMID 40564892, 2025). "Fluorescent lanthanide oxyfluoride nanoparticles conjugated with anti-CD-33 antibody for potential treatment of acute myeloid leukemia by conjugating PMI, a dodecameric peptide antagonist of MDM2 and MDMX and a CD-33-targeted humanized monoclonal antibody to nanoparticles via metal thiolate bonds." (PMID 38334567, 2024). "A bifunctional PD-1 × CD3 × CD33 immune checkpoint inhibitory T-cell engaging (CiTE) antibody simultaneously targeting PD-1, CD3 and CD33 has shown high therapeutic effect with complete AML (Acute Myelocytic Leukemia) eradication in preclinical experiments." (PMID 36389699, 2022). "CD13 and CD33 were the most frequently expressed aberrant markers in patients with ALL, whereas CD7 and CD19 were the most frequently expressed aberrant markers in patients with acute myeloid leukemia." (PMID 35350515, 2022). "In acute myelogenous leukaemia (AML) patients, exosomes were enriched in CD34, CD33 and CD117." (PMID 34830085, 2021). "A target antigen in acute myeloid leukemia (AML) is the myeloid differentiation antigen, CD33." (PMID 34361141, 2021). "Therefore, CD33 is a target for antagonistic mAbs and CAR-T cell immunotherapy, particularly in adult and pediatric acute myeloid leukemia (AML)." (PMID 34827170, 2021). "CD33 CAR expressing NK-92 cells showed no significant adverse side effects in a phase 1 trial for the treatment of acute myeloid leukaemia (AML) (NCT02944162)." (PMID 33923528, 2021). "In this category we can insert CD33, that is expressed by normal HSCs as well as by blasts of acute myelogenous leukemia (AML), but not at a high level as in CML LSCs." (PMID 34945101, 2021). "CAR T-cells therapy has an obvious barrier in acute myeloid leukemia (AML) because myeloid-directed immunotherapy will eradicate normal as well as malignant cells, leading to bone marrow failure, as has been shown in several preclinical studies of CD33 or CD123 directed CAR T cell therapy." (PMID 31950135, 2020). "CD33 is a myeloid differentiation antigen which is predominantly expressed on the cell surface of leukocytes of the myeloid lineage and with high frequency on myeloid leukemia cells, including acute myeloid leukemia (AML), chronic myeloid leukemia (CML) and myelodysplastic syndrome (MDS)." (PMID 29515764, 2018).
acute myeloid leukemia (continued). "In 2000, Mylotarg, a humanized IgG4 anti-CD33 antibody (hP67.6) conjugated to Calicheamicin via a hydrazone linker on lysine residues, was the first ADC to be approved by the FDA for the treatment of acute myeloid leukemia (AML) patients." (PMID 24454709, 2014). "Moreover, after intravenous administration into CD33+ human acute myeloid leukemia-bearing NOD-SCID mice, anti-CD33-EBV-specific T cells reached the tumor sites exerting antitumor activity in vivo." (PMID 22272203, 2012). "Among CAR-T therapies targeting acute myeloid leukemia (AML), single-target CAR-T therapies against CD33 or CD123 have shown certain success." (PMID 39844819, 2025). "Flow cytometry on peripheral blood revealed a diagnosis of acute myeloid leukemia (AML) with the blast cells expressing CD11b, CD11c, CD15, CD13, CD24, CD33, CD34, CD117, CD123 and HLA-DR." (PMID 41300735, 2025). "In acute myeloid leukemia (AML), CD302 is highly expressed in bone marrow immune populations and correlates positively with CD33, a clinical AML biomarker." (PMID 41323386, 2025). "In closing, she addressed the application of CAR-CIK cells to combat acute myeloid leukemia (AML) and explained how her team is currently working to characterize a trans-signaling dual CAR designed specifically for CD123 and CD33 target antigens." (PMID 38279995, 2024). "Current phase I/II clinical trials that engineer NK-92 cell lines with CARs to target CD19 (NCT02892695), CD33 (NCT02944162), CD7 (NCT02742727) on acute myeloid leukemia (AML) and acute lymphocytic leukemia (ALL) cells are ongoing." (PMID 39415291, 2024). "Similarly, in acute myeloid leukemia (AML) blasts, CD33 copy numbers may range from 1000 to 10,000 per cell." (PMID 37987250, 2023). "Gemtuzumab ozogamicin is the first approved CD33-targeting antibody-drug conjugate (ADC) and was used for induction therapy of acute myeloid leukemia (AML)." (PMID 33996901, 2021). "For example, the targeting of CD123 and CD33 in myelodysplastic syndrome (MDS) and in acute myeloid leukemia (AML) patients, respectively, results in toxicity due to the elimination of normal myeloid cells." (PMID 33117361, 2020). "For the treatment of acute myeloid leukemia (AML), AMG 330, a CD33/CD3 BiTE® antibody construct, has shown preclinical activity and is currently undergoing phase 1 clinical testing (NCT02520427)." (PMID 29855615, 2018). "Bone marrow immunophenotypic analyses revealed 23% blasts; positivity for CD34, HLADR and CD33; and negativity for CD7, CD19, CD10, CD117, CD36 and CD15, characterizing acute myeloid leukemia (AML), FAB classification M4." (PMID 28832804, 2018). "Two different CD33/CD16 bsAbs have been shown to efficiently kill acute myeloid leukemia (AML) cells or stem cells from myelodysplastic syndrome, a precursor of AML." (PMID 26284063, 2015). "CD33 is a promising target antigen for CAR-NK cell therapy, being expressed on the surface of leukemia cells in over 90% of patients with acute myeloid leukemia (AML)." (PMID 39007146, 2024). "Interestingly, CAR’TCR-T cells co-expressing CD33-CAR and dNPM1-TCR were developed to dually target acute myeloid leukemia (AML)." (PMID 39769267, 2024). "Nixdorf and colleagues designed and tested a biotin-directed AdCAR in combination with biotinylated anti-CD33, anti-human C-type lectin-like molecule-1 (CLL-1), or anti-CD123 AMs against acute myeloid leukemia (AML) cell lines and primary AML (pAML), both in vitro and in vivo." (PMID 38887285, 2024). "CD33, commonly expressed in a subpopulation in KMT2A-rearranged infant ALL, serves as an important immunophenotypic marker for the characterization of pediatric acute myeloid leukemia (AML) by EuroFlow and has been exploited as a therapeutic target for AML." (PMID 37740239, 2023). "Similar to pediatric acute myeloid leukemia (AML) the subgroup of biphenotypic acute lymphoblastic leukemia (ALL) is a rare complex entity with adverse outcome, characterized by the surface expression of CD33." (PMID 34398302, 2021).